MLPH (melanophilin)
Description:
Rab effector protein involved in melanosome transport. Serves as link between melanosome-bound RAB27A and the motor protein MYO5A.
Synonyms: SlaC2-a; l1Rk3; l(1)-3Rk; Slac-2a; ln; exophilin-3
Tractability: PROTAC: ubiquitination databases record sites on it.
Gene: Protein-coding gene on chromosome 2 (237,485,428 to 237,555,322, forward strand). Ensembl gene ENSG00000115648.
Subcellular location: Cytoplasm
Pathways (Reactome):
Developmental Biology: Regulation of MITF-M-dependent genes involved in pigmentation
Gene Ontology:
Molecular function: myosin binding; protein binding; protein-macromolecule adaptor activity; small GTPase binding; actin binding
Biological process: melanosome transport; intracellular protein transport
Cellular component: dendrite; extracellular exosome; perinuclear region of cytoplasm; cortical actin cytoskeleton; cytosol; cytoplasm
Genetic constraint (gnomAD): Loss-of-function variants: 50 observed, 73.9 expected, observed/expected ratio (o/e) 0.68, 90% interval 0.54 to 0.86. The upper end of that interval is the gene's LOEUF score, 0.86, which puts it in group 3 of 6, group 1 being the genes least tolerant of losing a copy. Missense variants: 743 observed, 789.14 expected, observed/expected ratio (o/e) 0.94, 90% interval 0.89 to 1. Synonymous variants: 301 observed, 323.69 expected, observed/expected ratio (o/e) 0.93, 90% interval 0.85 to 1.02.
Homologues: Orthologues: chimpanzee MLPH (98% identical), macaque MLPH (91% identical), rat Mlph (65% identical), mouse Mlph (64% identical), pig MLPH (61% identical), guinea pig MLPH (59% identical), dog MLPH (56% identical), rabbit MLPH (52% identical), tropical clawed frog mlph (42% identical), zebrafish mlpha (32% identical), zebrafish mlphb (29% identical). Paralogues in human: MYRIP (27% identical), MOBP (6% identical).
Diseases named in the same sentence as MLPH in open-access papers:
MLPH is named in the same sentence as 50 diseases in open-access papers, as found by Europe PMC text mining. Sharing a sentence is not in itself a finding about the gene and the disease. The quoted sentences say what the papers report.
breast carcinoma (16 papers, 2015 to 2023). "In our study, several genes of the top 10 down-regulated DEGs such as DUSP1, FOXA1, MLPH was implicated in the development of breast cancer." (PMID 26103053, 2015). "The top features in the BRCA-ER rSNFi signature include multiple genes known to be associated with breast carcinoma progression and outcome such as AGR3, B3GNT, and MLPH." (PMID 32714870, 2020). "Experiments have shown that a group of genes including MLPH can predict bone metastasis in breast cancer well." (PMID 31213036, 2019). "Furthermore, FOXA1 and MLPH upregulate the expression of luminal-like genes, and both have emerged as prognostic indicators for breast cancer." (PMID 38020889, 2023). "Remarkably, four well-described differentiating proteins in breast cancer subtypes, namely, Her2, Grb7, FOXA1 and MLPH, were clearly selected in the PAM50 as well as in the proteomic signatures." (PMID 26725330, 2016). "This cohort contained a subset of genes that could be considered potential biomarkers for breast cancer progression, including FOXA1, MLPH, ESR1, AR, GATA3, TFF1, THSD4, and TBC1D9." (PMID 38020889, 2023). "Our data show that the expression of POLR3G in breast cancer samples was negatively correlated with that of eight out of ten genes (GATA3; XBP1; AGR2; SIDT1; AR; SPDEF; FOXA1; MLPH) in a list of signature genes most differentially expressed in luminal A compared to basal-like tumors." (PMID 36497214, 2022).
Griscelli syndrome (11 papers, 2005 to 2025). Griscelli syndrome (GS) is characterized by silvery gray sheen of the hair and hypopigmentation of the skin which can be associated to neurological impairment (type 1), immunodeficiency (type 2) or be isolated (type 3). "Mutations in human MLPH can lead to Griscelli syndrome, which is characterized by abnormal skin pigmentation and light silver–white hair starting in infancy." (PMID 41394903, 2025). "Mutations in the MYO5A (MIM*160777) encoding MYO5A and MLPH (MIM*606526) encoding MLPH/SLAC2-A cause other types of Griscelli syndrome GS-1 (MIM#214450) and GS-3 (MIM#609227), respectively." (PMID 33362801, 2020). "In support of this region being functionally important, in another Rab associated disease, Griscelli Syndrome, a mutation in the switch 1 region of Rab27A results in a profound phenotype due to failure of the Rab protein to interact with its target melanophilin." (PMID 24516392, 2014). "On the other hand, mutations in the genes encoding MYO5A, RAB27A and MLPH are known to result in one of three subtypes of an autosomal recessive inherited human pigmentary diseases called Griscelli Syndrome (GS), which is mostly characterized as diluted pigmentation in skin and hair." (PMID 22844437, 2012). "Defects in any of these three genes, melanophilin (MLPH), myosin Va (MYO5A), and Rab27a (RAB27A), have been linked with several dilute phenotypes and the autosomal recessive Griscelli syndromes in humans (OMIM #214450, 607624, 609227)." (PMID 32512769, 2020). "In human, mutations within any of the genes RAB27A (RAB27A, member RAS oncogene family), MLPH (melanophilin), and MYO5A (myosin VA) encoding for the proteins of the tripartite complex can cause Griscelli syndromes." (PMID 24376820, 2013). "Several of the ciliary body/iris signature genes were noteworthy in that their mutation can lead to albinism or hypopigmentation phenotypes, including OA1 (ocular albinism type 1), TYR and TYRP1 (oculocutaneous albinism 1A and 3, respectively), and MLPH (Griscelli syndrome)." (PMID 16168081, 2005).
Griscelli syndrome type 3 (6 papers, 2013 to 2026). A Griscelli syndrome characterized by isolated silvery gray sheen of the hair and hypopigmentation of the skin that has material basis in mutation in the MLPH or MYO5A genes. "Mutations in MLPH cause Griscelli syndrome type 3 (GS3), which is characterized by hypopigmentation of the skin and hair." (PMID 39228912, 2024). "Griscelli syndrome type 3 (GS3) is caused by mutations in the MLPH gene." (PMID 35602484, 2022). "Griscelli syndrome type 3 (GS3) is caused by mutations within MLPH or MYO5A and only MLPH defects are usually not accompanied by severe clinical diseases." (PMID 24376820, 2013). "The dilution phenotype of the human Griscelli syndrome type 3 caused by MLPH mutations is usually not accompanied by severe clinical diseases." (PMID 24376820, 2013).
melanoma (6 papers, 2011 to 2024). A malignant, usually aggressive tumor composed of atypical, neoplastic melanocytes. "MLPH, Rab27a, and Myo5a form ternary complexes, which play a key role in the transfer of melanoma bodies from melanocytes to neighboring keratinocytes and ultimately color the animal coat." (PMID 33466315, 2021). "In melanoma, MLPH blocker inhibits melanoma cell motility and invasion." (PMID 39308678, 2024). "Moreover, moderate to high melanophilin expression has been commonly observed in patients with advanced-stage melanoma." (PMID 34829479, 2021). "B16F10 cells cultured with wogonoside and norwogonin showed almost no detectable reduction in the protein level of MLPH when compared with wogonin-treated melanoma cells." (PMID 28182699, 2017). "In addition, other genes known to be expressed in melanocytes, including MLANA, SILV, EDNRB and melanophilin, were also detected in these EGIR specimens overlying melanoma." (PMID 21294715, 2011).
albinism (4 papers, 2005 to 2024). A congenital disorder characterized by partial or complete absence of melanin pigment in the eyes, hair, or skin. "The Rab27a mutation that impairs both the exophilin-4 and Munc13-4 interactions but retains the melanophilin interaction causes hemophagocytic lymphohistiocytosis without albinism, which suggests that, in contrast to melanophilin, exophilin-4 is dispensable for melanosome transfer to keratinocytes." (PMID 34483204, 2021). "These variations are caused by mutations in three genes located on the 15q21 region, i.e., MYO5A, RAB27A, and MLPH, giving rise to three distinct clinical forms, respectively, GS1, GS2, and GS3, with albinism as a common feature." (PMID 38993473, 2024).
prostate carcinoma (4 papers, 2013 to 2024). A carcinoma that arises from epithelial cells of the prostate gland. "While its role in cancer is not well understood, recent research has found that MLPH is associated with tumor development and metastasis in skin, breast, and prostate cancer." (PMID 38608841, 2024).
Chediak-Higashi syndrome (3 papers, 2017 to 2021). ChC)diak-Higashi syndrome (CHS) is a rare severe genetic disorder generally characterized by partial oculocutaneous albinism (OCA), severe immunodeficiency, mild bleeding, neurological dysfunction and lymphoproliferative disorder. "In addition, NGS did not reveal pathogenic/likely pathogenic variants in the genes associated with Griscelli syndrome type 1-3 (MYO5A, RAB27A, MLPH) or Chediak–Higashi syndrome (LYST)." (PMID 34685610, 2021).
lung cancer (3 papers, 2010 to 2016). A malignant neoplasm involving the lung. "The four genes with lung cancer-associated alternative splice forms newly identified in this study were: CEACAM1, FHL1, MLPH, and SUSD2." (PMID 20525254, 2010). "Of them, 6 miRNAs (miR-149, miR-205, miR-375, miR-378, miR-422a and miR-708) and 9 target genes (CEACAM6, CGN, CLDN3, ABCC3, MLPH, ACSL5, TMEM45B, MUC1) were validated by quantitative PCR in an independent cohort of 41 lung cancer patients." (PMID 24625834, 2014).
pancreatic cancer (3 papers, 2023 to 2025). "MLPH is highly expressed in high-grade tumors, suggesting that it is associated with tumor prognosis and may be a potential target for pancreatic cancer therapy." (PMID 39308678, 2024). "Melanophilin (MLPH) is involved in the progression of various tumors, but its molecular mechanisms and role in pancreatic cancer progression are unknown." (PMID 39308678, 2024). "To validate the effect of MLPH on pancreatic cancer in vivo, we constructed a subcutaneous xenograft model using SUIT-2 cells after MLPH knockdown and overexpression (n =5/group)." (PMID 39308678, 2024). "In the present study, the KEGG enrichment analysis demonstrated that MLPH expression in pancreatic cancer correlated significantly with the PI3K-AKT pathway, suggesting that MLPH might regulate EMT in PAAD through the PI3K-AKT pathway." (PMID 39308678, 2024).
rectal cancer (3 papers, 2021 to 2025). A primary or metastatic malignant neoplasm that affects the rectum. "Here, we are interested in MLPH as the overexpression of MLPH has been associated with poorer patient survival and increased metastasis in prostate and rectal cancers." (PMID 39820281, 2025). "In rectal cancer, high MLPH expression in patients was associated with poorer preoperative radiotherapy response and lower survival." (PMID 39308678, 2024). "High MLPH expression in patients with rectal cancer has exhibited association with poorer preoperative radiotherapy response and lower survival." (PMID 39308678, 2024). "Therefore, our current study aimed to investigate the association between MLPH expression and clinical outcomes, including tumor response to preoperative chemoradiation and survival, in our 172 rectal cancer patients treated with preoperative chemoradiation." (PMID 34829479, 2021). "After dividing our rectal cancer patients into groups with high and low MLPH expression, immunohistochemical staining was performed to assess the relationship of this factor with clinicopathologic characteristics." (PMID 34829479, 2021). "This study is the first to reveal that MLPH expression can be a prognostic marker for rectal cancer outcomes." (PMID 34829479, 2021). "Data mining of a public transcriptomic rectal cancer dataset (GSE35452) from the NCBI GEO identified the MLPH gene as the most significantly intracellular protein transport-related gene (GO:0006886) associated with poor response to preoperative chemoradiotherapy." (PMID 34829479, 2021).
alopecia (2 papers, 2021). Hair loss usually from the scalp. "However, MLPH mutant dogs are predisposed to developing color dilution alopecia." (PMID 34680875, 2021).
breast invasive carcinoma (2 papers, 2022 to 2024). "The GEPIA 2 database analysis demonstrated that MLPH expression was upregulated in breast invasive carcinoma, PAAD, prostate adenocarcinoma, and skin melanoma." (PMID 39308678, 2024).
breast tumors (2 papers, 2015 to 2022). "The top eight genes that negatively correlated to POLR3G expression (MLPH, FOXA1, SPDEF, AR, SIDT1, AGRP2, XBP1, GATA3) are typically overexpressed in ER+ breast tumors as compared to ER- breast tumors." (PMID 36497214, 2022).
prostate tumors (2 papers, 2016). "The expression of MLPH in primary prostate tumors was significantly lower in those with the G compared with the T allele and correlated significantly with AR protein." (PMID 26411452, 2016). "Of these, EFHD1, MLPH, NAALADL2 and KLK15 are significantly upregulated while others are downregulated in prostate tumors compared to normal samples." (PMID 27409348, 2016).
asthenozoospermia (1 paper, 2023). "The proteins RAB10, RAB3D, RAB27A, and MLPH that showed a lower abundance level in asthenozoospermia and a higher abundance level in oligoasthenozoospermia were either Ras-related or were associated with sperm motility and capacitation." (PMID 37048090, 2023).
cervical cancer (1 paper, 2024). A primary or metastatic malignant neoplasm involving the cervix. "Contrastingly, MLPH expression was downregulated in cervical cancer, lung squamous carcinoma, thyroid cancer, and uterine sarcoma." (PMID 39308678, 2024).
colorectal cancer (1 paper, 2021). A primary or metastatic malignant neoplasm that affects the colon or rectum. "Although the association between MLPH expression and colorectal cancer outcomes remains unknown, our study is the first to demonstrate that a high expression of MLPH is associated with a poor response to preoperative chemoradiation and confers a negative impact on survival (DSS, LRFS, and MeFS)." (PMID 34829479, 2021).
endometrial cancer (1 paper, 2018). Primary or metastatic malignant neoplasm involving the endometrium (mucous membrane that lines the endometrial cavity). "Furthermore, the expression of estrogen-responsive genes KIAA1324, MLPH, MSX2, SPDEF, TFF3, and PIGR were all significantly up-regulated in CTCF-altered endometrial cancers (p = 0.0004, 0.0007, 0.0032, 0.0009, 0.0122, and 0.0028 respectively)." (PMID 30513694, 2018).
Hemophagocytosis (1 paper, 2014). Phagocytosis by macrophages of erythrocytes, leukocytes, platelets, and their precursors in bone marrow and other tissues. "GS2 is distinguished from other subtypes of GS (GS1: mutation in MYO5A encoding myosin Va; GS3: mutation in MLPH encoding melanophilin) from the fact that only GS2 is associated with the development of hemophagocytosis." (PMID 24478771, 2014).
lung adenocarcinoma (1 paper, 2024). A carcinoma that arises from the lung and is characterized by the presence of malignant glandular epithelial cells. "Meanwhile, several studies demonstrated that MLPH was highly expressed in lung adenocarcinoma but not in squamous cell carcinoma, indicating that MLPH could be a potential marker for differential diagnosis." (PMID 38608841, 2024).
meningioma (1 paper, 2018). A generally slow growing tumor attached to the dura mater. "Our data show that MLPH underexpression was usually associated with more aggressive meningiomas." (PMID 29662628, 2018). "MLPH, encoding a G-protein with roles in melanosome transport, has been shown to be differentially expressed in less aggressive (benign) histologic variants of meningioma." (PMID 29662628, 2018). "RUNDC3B, SCG2, SLC1A3, EXT1 (as well as RHOBTB3, TSPAN7, CAV2, MLPH) were part of the NF2/SMARCB1 expression subclass of a recent study on genomic profiling of meningioma." (PMID 29662628, 2018).
preeclampsia (1 paper, 2026). Preeclampsia is a hypertensive disorder of pregnancy that is characterized by new-onset hypertension with proteinuria presenting after 20 weeks of gestation, and depending on mild or severe forms may initially present with severe headache, visual disturbances, and hyperreflexia. "Melanophilin expression was reduced during cytotrophoblast syncytialization; however, excessive loss disrupted syncytiotrophoblast function, triggering the production of factors known to drive preeclampsia." (PMID 42253923, 2026). "To validate our findings, we focused on melanophilin, a gene downregulated in the early pregnancy placenta of term preeclampsia." (PMID 42253923, 2026).
Spitz nevi (1 paper, 2022). "An additional fusion partner, MLPH (melanophilin), involved in melanosome trafficking, has been recently described in pediatric Spitz nevi." (PMID 35747831, 2022).